ZFYVE27 (zinc finger FYVE-type containing 27)
Description:
Molecular tethering protein, which plays a role in the formation of membrane contact sites between the endoplasmic reticulum and late endosomes/lysosomes. Promotes neurite formation by tethering endosomes to the endoplasmic reticulum membrane: interacts with Rab7-positive late endosomes, acting as a bridge to form endoplasmic reticulum membrane-endosome contact sites. Acts in cooperation with vesicle-associated membrane protein-associated protein (VAPA or VAPB), thereby facilitating loading of the endosome membrane with KIF5, which is required for movement of the endosomes along microtubules in the plus-end direction. Also associates with Rab11-positive recycling endosomes, facilitating exocytosis and membrane expansion. Contributes to both the formation and stabilization of the tubular endoplasmic reticulum network. Involved in endoplasmic reticulum morphogenesis by regulating the sheet-to-tubule balance and possibly the density of tubule interconnections.
Synonyms: SPG33; FLJ32919; PROTRUDIN
Tractability: Antibody: UniProt predicts a signal peptide or a membrane-spanning region; its Gene Ontology location is reachable by antibodies, with medium confidence. PROTAC: ubiquitination databases record sites on it.
Gene: Protein-coding gene on chromosome 10 (97,737,117 to 97,760,907, forward strand). Ensembl gene ENSG00000155256.
Subcellular location: Endoplasmic reticulum membrane; Late endosome membrane; Recycling endosome membrane; Cell projection, growth cone membrane
Subcellular location (Human Protein Atlas): Nucleoplasm; Vesicles; Cytosol
Gene Ontology:
Molecular function: endoplasmic reticulum-endosome tether activity; identical protein binding; protein binding; metal ion binding
Biological process: endoplasmic reticulum tubular network formation; neuron projection development; organelle localization by membrane tethering; vesicle-mediated transport; neurotrophin TRK receptor signaling pathway; positive regulation of axon extension; protein localization to plasma membrane
Cellular component: endoplasmic reticulum; endoplasmic reticulum membrane; endoplasmic reticulum tubular network; endoplasmic reticulum-endosome membrane contact site; axon; dendrite; growth cone membrane; recycling endosome membrane; cytoplasm; endomembrane system; late endosome membrane; membrane
Genetic constraint (gnomAD): Loss-of-function variants: 36 observed, 54.51 expected, observed/expected ratio (o/e) 0.66, 90% interval 0.5 to 0.87. The upper end of that interval is the gene's LOEUF score, 0.87, which puts it in group 3 of 6, group 1 being the genes least tolerant of losing a copy. Missense variants: 450 observed, 548.45 expected, observed/expected ratio (o/e) 0.82, 90% interval 0.76 to 0.89. Synonymous variants: 223 observed, 226.17 expected, observed/expected ratio (o/e) 0.99, 90% interval 0.88 to 1.1.
Gene-disease validity (ClinGen):
ClinGen rates the evidence that ZFYVE27 causes each of these diseases.
hereditary spastic paraplegia 33 (autosomal dominant): Disputed. Any hereditary spastic paraplegia in which the cause of the disease is a mutation in the ZFYVE27 gene.
Homologues: Orthologues: chimpanzee ZFYVE27 (99% identical), rabbit ZFYVE27 (94% identical), pig ZFYVE27 (92% identical), mouse Zfyve27 (88% identical), macaque ZFYVE27 (87% identical), rat Zfyve27 (87% identical), dog ZFYVE27 (74% identical), tropical clawed frog zfyve27 (62% identical), zebrafish zfyve27 (47% identical), guinea pig Zfyve27 (41% identical).
Diseases named in the same sentence as ZFYVE27 in open-access papers:
ZFYVE27 is named in the same sentence as 8 diseases in open-access papers, as found by Europe PMC text mining. Sharing a sentence is not in itself a finding about the gene and the disease. The quoted sentences say what the papers report.
Spastic paraplegia (3 papers, 2019 to 2022). Complete loss of the ability to move the lower limbs accompanied by spasticity of the lower limbs. "Protrudin is an ER-shaping protein with an HP domain, and its gene (ZFYVE27) is mutated in a subset of individuals with HSP, with protrudin also being referred to as spastic paraplegia (SPG) 3317,28." (PMID 32917905, 2020). "Lastly, mutations in two genes called protrudin (ZFYVE27) and spastizin (ZFYVE26), which encode FYVE domain-containing proteins, cause subtypes of spastic paraplegia (MIM 610244 and MIM 270700, respectively)." (PMID 31413155, 2019).
hereditary spastic paraplegia (2 papers, 2012 to 2018). Hereditary spastic paraplegias (HSP) comprise a genetically and clinically heterogeneous group of neurodegenerative disorders characterized by progressive spasticity and hyperreflexia of the lower limbs. "Network 24 contained also several genes previously associated with neurological diseases, like ZFYVE27 (hereditary spastic paraplegia), ATB1B1 (neurodegeneration of photoreceptors) and SPG21 (Mast syndrome)." (PMID 23028713, 2012). "Interestingly, ZFYVE27 gene has recently been associated with hereditary spastic paraplegia (HSP), as mutations in ZFYVE27 were detected in HSP patients." (PMID 30283000, 2018).
neuritis (1 paper, 2012). A neuropathy arising from inflammation of one or more nerves. "Also, genes involved in nervous system development were found, for example ATP1B1 (involved in aggregation of neurons), TRIM2 (neuroprotection of cortical neurons) and VAPA, SGK1 and ZFYVE27 (involved in morphogenesis of neuritis)." (PMID 23028713, 2012).
paraplegia (1 paper, 2023). Complete paralysis of the lower half of the body including both legs, often caused by damage to the spinal cord. "FYCO1 also has interaction potential with CCZ1B involved in vacuolar transport, ZFYVE27 (the spastic paraplegia gene), CXCR6, and SASS6 involved in centriole duplication." (PMID 37629644, 2023).
pericarditis (1 paper, 2026). An inflammatory process affecting the pericardium. "Among them, elevated levels of NEU1, GDNF, and LAT increased the risk of pericarditis, whereas higher levels of CASP8, ZFYVE27, and NAPA decreased the risk of pericarditis." (PMID 41674924, 2026).
cancer (1 paper, 2023). A tumor composed of atypical neoplastic, often pleomorphic cells that invade other tissues. "Levels of proteins Rngtt, Rp1l1, Tacstd2, Zfyve26, and Zfyve27, which are known to promote a proliferative phenotype in various cancers, were decreased in the brain vasculature of TGF mice, likely as an attempt to attenuate vascular proliferation and remodeling." (PMID 38132326, 2023).
ZFYVE27 also shares sentences with these, for which no sentence is quoted: mast syndrome (1 paper); neurological diseases (1).